CXCR3 (C-X-C motif chemokine receptor 3)
Diseases named in the same sentence as CXCR3 in open-access papers (continued):
Sharing a sentence is not in itself a finding about the gene and the disease.
cancer (continued). "Moreover, the proportion of CXCR3+ cancer cells was significantly higher when cultured under serum-free sphere conditions, and tended to be higher in lung metastatic derivatives compared with parental counterparts." (PMID 32198421, 2020). "Given the complexity of the splice variants and expression of CXCR3 on activated T cells, additional research is needed to determine if and how TEC-expressed CXCR3 may be targeted for cancer immunotherapeutic purposes." (PMID 30800123, 2019). "CXCR3 expression might be of special interest with respect to cancer treatment since it regulates recruitment of NK cells into solid tumors." (PMID 31457007, 2019). "To determine whether CXCR3 isoform levels correlate with cancer cell phenotype, we compared the expression of CXCR3 isoforms in PD153035-induced epithelial transitioned DU145 cells." (PMID 31831069, 2019). "This shift of CXCR3 isoform usage appeared to loosely parallel that of E-cadherin, the main and only consistent marker of the epithelial phenotype in carcinoma cells during progression, which is down-regulated to variable degrees during both primary and secondary EMT of cancer progression." (PMID 31831069, 2019). "CXCR3 is reported to play a dual role in immunity and cancer." (PMID 29690901, 2018). "Inflammation may promote CXCR3 upregulation in PTC by inducing its promoter demethylation or by demethylation of intron CpG sites resulting in increased CXCR3A levels in cancer cells." (PMID 29416784, 2018). "Moreover, the CXCR3-alt-high cancer tissue was characterized by low CXCL4 and high CXCL11 expression." (PMID 29379506, 2017). "CXCR3 plays important roles in angiogenesis, inflammation, and cancer." (PMID 29146996, 2017). "The chemokine receptor CXCR3 plays important roles in angiogenesis, inflammation and cancer." (PMID 28878333, 2017). "It has been reported that CXCR3 can promote metastasis in some types of cancer." (PMID 28384236, 2017). "As studied extensively, Tregs isolated from healthy donors and cancer patients can express a plethora of chemokine receptors (CCR2-9, CXCR3/4) and migrate efficiently in vitro in response to tumor-derived chemokines, typically secreted by cancer cells or innate immune cells." (PMID 27509527, 2016). "In addition, it was found that CXCR3 was expressed significantly in cancer tissues (29/40, 72.5%) through employing the western blot." (PMID 26883105, 2016). "The CXCL10/CXCR3 axis has been regarded as an important regulator in cancer cell invasion." (PMID 26506595, 2016). "Increased expression of CXCR3 has been correlated with hypoxia and nutrient deprivation in vitro, suggesting that cells expressing CXCR3 can survive and grow in the less favorable microenvironments of advanced cancer." (PMID 25798946, 2015). "Although the chemokine receptor, CXCR3, is normally expressed on activated lymphocytes and involved in directing their migration to damaged tissue, it is also expressed on many human and murine cancer cells." (PMID 25798946, 2015). "Indeed, recent research found that Cxcl10 and its receptor Cxcr3 were involved in inflammatory pain and cancer pain." (PMID 26184882, 2015). "In addition, a subset of these genes have been identified as markers for poor outcomes in lymphoid and other cancers (CXCR3, EOMES, BUB1)." (PMID 22053823, 2011). "With respect to immune cell infiltration in cancer, CXCR3, along with IFN-γ, may play an important role with respect to NK cell infiltration." (PMID 20429924, 2010). "It is, therefore, tempting to speculate that the CXCR3/chemokines axis may facilitate implantation, growth/survival and expansion of the cancer cells within lung tissues." (PMID 19436305, 2009). "We, therefore, performed experimental metastatic models that selectively address the impact of CXCR3 blockade on the extravasation step of the CRC cells by inoculating the cancer cells into mice through intravenous injections in both the hepatic and the pulmonary models." (PMID 19436305, 2009).
cancer (continued). "Therefore, focusing research on alternative downstream pathways of CXCR3 in cancer may lead to the development of more selective therapies with lower risks of off-target toxicity than those associated with broad kinase inhibitors." (PMID 38104126, 2023). "Furthermore, CXCR3 plays a significant role in immune infiltration in cancer." (PMID 36030223, 2022). "In the present study, we used the median CXCR3 pathway activation values for the ICI and TCGA cohorts to categorize patients as CXCR3-high or CXCR3-low; however, different cancers may have different levels of CXCR3 activation, which makes this threshold difficult to apply in the clinical setting." (PMID 35562800, 2022). "In addition, compared with untreated tumors, tumors treated with SGT-53 showed increased mRNA expression of chemokines including Cxcl9, Cxcl10, and Cxcl12, which are associated with increased infiltration of activated T cells in various human cancers via the chemokine receptors CXCR3 and CXCR4." (PMID 36359830, 2022). "However, we discovered that ATS may have an immunosuppressive effect by downregulating the expression of key chemokines such as CXCL9, CXCL10, and CXCR3, and therefore decreasing the cancer immunity." (PMID 36302799, 2022). "Enhancement of paracrine CXCR3 ligands (CXCL9, CXCL-10, and CXCL-11) in the tumor microenvironment and deactivation of CXCR3 expression on cancer cells could be antitumorigenic by recruiting activated natural killer cells and T lymphocytes with potent antitumor effects in various lung cancer models." (PMID 36164329, 2022). "Next, we analyzed the relationships of LCK with IFNG, CCL5, and CXCR3, using TCGA bulk RNA-sequencing data, and we found significant associations in the expression levels of LCK with IFNG (total rho=0.73), CCL5 (total rho=0.80), and CXCR3 (total rho=0.84) in most cancer types." (PMID 35069521, 2021). "Furthermore, CXCR3 can regulate the growth and metastasis of cancers." (PMID 33407095, 2021). "However, we found that Siglec15 may exert an immunosuppressive function by comprehensively downregulating the expression of critical immunomodulators such as CXCL9, CXCL10, and CXCR3, and subsequently downregulating the activities of the cancer-immunity cycle." (PMID 33537076, 2021). "Therefore, CXCR3+ cancer cells may be enriched in metastatic stem cells that are equipped to exploit the metastasis-promoting paracrine loop with fibroblasts." (PMID 32198421, 2020). "Besides, CXCR3 was found to be expressed by immune cells (macrophages, T cells, and dendritic cells), and CXCR3+leukocytes could be differentiated and recruited through paracrine signals to induce or inhibit cancer growth." (PMID 33324682, 2020). "The role of the CXCR3 chemokine system in cancer biology may be a double-edged sword." (PMID 31482487, 2019). "In addition, it is possible that skin CXCR3+ T cells may promote inflammation-driven cancer development in some instances." (PMID 30320116, 2018). "Thus, differential responsiveness of carcinoma cells may be due to either the cellular milieu or the CXCR3 isoform presentation." (PMID 22236567, 2012). "Moreover, this cancer immune escape could be reversed by reintroducing CXCR3 into the T cells." (PMID 39940842, 2025). "In particular, chemokines, including CXCL8, CXCL10, CXCL11, CXCL16, CCL26, and CCL7, as well as chemokine receptors, including CXCR3, CCR2, CCR5, and CCR1, were positively correlated with MRPL13 expression in various cancer types." (PMID 37827692, 2023). "The function of the CXCL9, -10, -11/CXCR3 axis in response to IFN-γ is mainly divided into two directions: paracrine signaling for immune activation and autocrine signaling for cancer cell proliferation and metastasis." (PMID 38143766, 2023). "CXCR3 has three different isoforms in humans, CXCR3A, CXCR3B, and CXCR3Alt, and its dual role in immune response and cancer has been reported." (PMID 35978426, 2022).
cancer (continued). "M2 macrophages (C6-Mye) were predicted to secrete the factors CXCL12 and CCL4 to attract CD8+ Tex cells by binding to CXCR3/CXCR4 and CCR5 on CD8+ Tex cells, which are known to recruit immunocytes into cancer tissues." (PMID 35562760, 2022). "However, only a few preclinical experiments have explored the relationship between CXCR3 signaling pathway and cancer immunotherapy, and due to the complexity of the immune system, immune responses may vary in different individuals and different types of tumors." (PMID 35562800, 2022). "The CCL4/CCR5 axis, CXCL9/CXCR3-axis, and CXCL13/CXCR5-axis have previously been shown to promote cancer progression and metastasis." (PMID 36163179, 2022). "In contrast, CXCR3, an anti-tumor receptor of ICIs, was shown to be upregulated in PTPRD/PTPRT mutant cancers (P <0.001)." (PMID 36248841, 2022). "Our findings point to therapeutic limitations of ongoing efforts to selectively target CXCR3, CXCR4, or CXCR7 in cancer patients, and rather favor individualized targeting strategies." (PMID 36539774, 2022). "Intriguingly, Flt3L mRNA correlated to the markers of a metagene signature indicative of immunogenic cancer cell death, which encompassed Caspase1 (CASP1), Perforin 1 (PRF1) and Chemokine receptor CXCR3 (CXCR3)." (PMID 34503273, 2021). "Oncologically, CXCL10, with its receptor C-X-C motif chemokine receptor 3 (CXCR3), facilitates cancer cell proliferation, metastasis, and invasion." (PMID 33990548, 2021). "miR-561-5p with high expression in HCC directly target to reduce the expression of CXCL3, reduce the infiltration of CXCR3+ NK cell subtypes in TME, promote the survival of cancer cells, and promote lung metastasis." (PMID 33869023, 2021). "A part from chemotaxis, CXCL10 have been reported to promote cancer invasion and to increase invasive properties of RA FLS in vitro in a CXCR3-dependent autocrine fashion." (PMID 31275320, 2019). "Detailed researches on the functions of CXCL12‐CXCR4/CXCR7 pathways and their cross‐talks with CXCR3, CXCL11, CXCL10, and CXCL9 remain urgently warranted, which help lead to safer and more efficient use of their molecular inhibitors in targeted cancer therapy." (PMID 28544785, 2017). "CD26high T cells expressed Th1/Th17 chemokine receptors (CCR6, CXCR3, and CD161), whereas CD26neg T cells expressed CXCR3, confirming that cell subsets within these cultures are comparable between cancer patients and healthy individuals." (PMID 29213079, 2017). "Transcriptional expression of CXCR3 and CCR5 cognate chemokines correlate withCD8+ T-cell infiltration and prolonged survival incolorectal cancer (CRC)." (PMID 25671296, 2015). "Many of these genes function in inflammation (CXCR3, EOMES, IL18R1, GZMM, IL2rb), metastases (CXCR3, BUB1), poor outcome cancers (EOMES, BUB1), or stem cells (EOMES, BUB1)." (PMID 22053823, 2011). "Elevated CXCR3 expression in primary T-ALL samples compared with normal thymic cells further strengthens its therapeutic potential, and strategies targeting CXCR3 have already been explored in several cancers and inflammatory diseases." (PMID 41129238, 2026). "CXCR3—also called G-protein-coupled receptor 9 or CD183—is an interferon-induced chemokine receptor that can be expressed on NK T cells, monocytes, CD8+ T cells, Th1 T cells, NK cells, dendritic cells, and cancer cells." (PMID 36611975, 2023). "CXCR3 (GPR9/CD183) is an interferon‐inducible chemokine receptor, which is predominantly expressed on monocytes, Th1 cells, CD8 T cells, NKT cells, NK cells, DC and cancer cells." (PMID 37170733, 2023). "Based on our findings, we postulate that this is due to an enhanced immune infiltration and/or activation, and not to a PD-L1 upregulation that has been attributed to CXCR3 chemokines in the cancer microenvironment before." (PMID 35314795, 2022).
cancer (continued). "CXCL9, CXCL10, and CXCL11 are ligands of the chemokine receptor CXCR3, which is preferentially expressed by CD4+ and CD8+ T cells, but could also be detected on the surfaces of cancer cells." (PMID 36428508, 2022). "Additionally, the expression of CXCL4 and its receptor CXCR3 are observed to be downregulated in clear cell OC, possibly due to TAM inhibition, creating a microenvironment suitable for cancer cell growth." (PMID 35269786, 2022). "Finally, we validated our findings on the relationship between CXCR3 pathway activation and ICI effectiveness in cohorts of other types of cancer." (PMID 35562800, 2022). "The correlation of high CXCR3 expression and better survival found in BRCA could be due to increased CXCR3-B expression within cancer cells." (PMID 34440489, 2021). "In line with this, CM from CXCR3+ cancer cells, but not from CXCR3− cells, induced high CXCL10 expression in mouse and human lung fibroblasts." (PMID 32198421, 2020). "Interestingly, flow cytometric analysis revealed that CXCR3 is expressed by a subpopulation of MDA and SUM cancer cells and their metastatic derivatives." (PMID 32198421, 2020). "The mechanisms regulating CXCR3 expression, particularly expression induced by IL-17A, on CD8+ T cells in cancer remain largely unknown." (PMID 32503584, 2020). "PDAC tumors have a subset of highly overexpressed (and highly expressed in terms of magnitude) chemokine receptors (CCR6, CCR7, CXCR3 and CXCR4) not expressed in PDAC cancer cells but likely associated with immune cells and their activation." (PMID 31765370, 2019). "Thus, we suggest that cleavage of the ligands of the CXCR3 and CX3CR1 chemokine systems represents a potent immune escape mechanism in cancer." (PMID 31482487, 2019). "CXCR3 (GPR9/CD183) is an interferon-inducible chemokine receptor expressed on various cell types, but preferentially monocytes, Th1 T cells, CD8 T cells, NKT cells, NK cells, dendritic cells, and some cancer cells." (PMID 30320116, 2018). "WEV+NP showed greater activities than WEV alone in decreasing the surface expression of the chemokine receptors CXCR3, CXCR4 and CXCR6 and decreased migration of the cancer cells, suggesting this approach possesses the promising therapeutic potential for clinical application of snake venoms." (PMID 30158426, 2018). "The results showed that CXCR3 was predominately expressed in cell membrane and cytoplasm, and was upregulated significantly in cancer tissues in comparison with the corresponding adjacent noncancerous tissues(27/40, 67.5%)." (PMID 26883105, 2016). "However, the increasing knowledge gained through cancer research has gradually led to the realization that cancer is a complex systemic disease and that the TME plays an important role in tumor receptors, while CXCR3 also has a unique role in the TME." (PMID 39429695, 2024). "More importantly, PIIO-1 showed therapeutic efficacy against both GARP+ and GARP- cancers alone or in combination with anti-PD-1 antibody, by preventing T cell exhaustion and enhancing CD8+ T cell migration into the TME in a C-X-C motif chemokine receptor 3 (CXCR3)-dependent manner." (PMID 38514615, 2024). "Notably, CXCR3, CD8B, and ENTPD1 were identified as potent protective factors against six cancers." (PMID 38627900, 2024). "Mixtures of CXCL4 and CXCL12 or obligate CXCL4•CXCL12 heterodimers inhibited CXCL12-induced migration of breast MDA-MB-231 cancer cells, increased Ca2+ release and activated downstream signaling of CXCR4 but not of CXCR3, highlighting its role in the limitation of cancer progression." (PMID 37446102, 2023). "In the cancer-immunity cycle, the C–C motif chemokine receptor 7 (CCR7)-CCL19/CCL21 axis governs the entry of cDC1 and TN into the TdLN, while the C-X-C motif chemokine receptor 3 (CXCR3)-CXCL9/CXCL10 axis regulates the egress of T helper 1 (Th1) cells and CD8+ TSTs from the TdLN into the TIME." (PMID 38044445, 2023).
cancer (continued). "The mixture of CXCL4 and CXCL12 or the obligate CXCL4•CXCL12 heterodimer inhibited CXCL12-induced migration of MDA-MB-231 breast cancer cells, increased cytoplasmic Ca2+ release and activated downstream signaling of CXCR4 but not CXCR3, highlighting its role in limiting cancer progression." (PMID 37446102, 2023). "Furthermore, we provided new insights that CXCL10 through TLR4, instead of CXCR3, mobilized monocytic MDSCs, but not granulocytic MDSCs, to the liver for facilitating cancer recurrence using CXCL10−/−, CXCR3−/− and TLR4−/− mice." (PMID 33990548, 2021). "CXCL10 and CXCL11 are ligands of chemokine CXCR3, which can regulate the migration, differentiation and activation of immune cells, and are related to the selective migration and linear development of CD4 + and CD8 + T cells, thereby affecting the therapeutic effect of cancer." (PMID 35087563, 2021). "Also, mRNA level of CXCR3 were examined, the result showed that CXCR3 expression was predominately higher in cancer tissues than the corresponding adjacent noncancerous tissues (63/89, 70.79%)." (PMID 26883105, 2016). "SW620 cell lines with reduced expression of CXCR3 and/or CXCR4 created using microRNA, CXCR3-, CXCR4-, and CXCR3/ CXCR4 double-knockdowns significantly reduces metastasis to lymph nodes, liver and lungs, and significantly decreases the dissemination of cancer cells to liver and lungs." (PMID 24647809, 2014). "It has been reported that the cancer autocrine molecule C-X-C motif chemokine 11 (CXCL11), accumulated in the TME, could increase the expression of stemness-related genes and maintain the stem cell features of α2δ1+ liver CSCs through chemokine (C-X-C motif) receptor 3 (CXCR3)/ERK1/2 signaling." (PMID 36293184, 2022).
inflammation (13 papers, 2008 to 2025). Aberrant reaction of the microcirculation characterized by movement of fluid and leukocytes from the blood into extravascular tissues. "CXCL11 is a chemokine that attracts CXCR3+ T cells and is implicated in synovial inflammation in RA." (PMID 40606440, 2025). "Elevated hepatic CXCR3 expression, and peripheral CXCR3 chemokine levels, have been associated with liver inflammation and fibrosis in chronic HCV." (PMID 27309850, 2016). "In severe respiratory viral infection, IP-10 was reported to attract inflamed CXCR3+ neutrophils, resulting in fulminant pulmonary inflammation." (PMID 37701855, 2023). "The frequency of CXCR3+ Treg cells declined with decreased Teff cell-induced inflammation suggesting that pancreatic inflammation promotes the induction of CXCR3 on Treg cells (40% at 1:12 ratio, 30% at 1:5 ratios, and 21% with Treg cells alone)." (PMID 25946021, 2015). "Further studies to specifically deleting CXCR3 in retinal neurons, microglia, and blood leukocytes are required to explore the precise mechanisms of CXCR3-induced retinal inflammation and neuronal injury in acute glaucoma." (PMID 26448323, 2015). "In this study, we have demonstrated that deletion of CXCR3 gene in mice significantly prevented the lung inflammation induced by exposure to CS." (PMID 19087279, 2008). "Higher amounts of HBV/HDV-unspecific CD4 T cells expressing CXCR3 may contribute to the aggravated liver inflammation frequently observed in patients with CHD." (PMID 39980752, 2025). "Thus, targeting the CXCL10 receptor CXCR3 is a promising therapeutic approach to treating cardiac inflammation." (PMID 27795961, 2016). "By blocking CXCR3 with gene deletion or activating CXCR3 with intravitreal injection of CXCL10, we clearly demonstrate that CXCR3 is involved in retinal inflammation, oxidative, and nitrosative stress, and retinal neuronal death during acute glaucoma." (PMID 26448323, 2015).